IL1B (interleukin 1 beta)
Diseases named in the same sentence as IL1B in open-access papers (continued):
Sharing a sentence is not in itself a finding about the gene and the disease.
infection (continued). "In contrast, we assayed the macrophage line THP-1 infected with T. gondii and showed they made a robust IL-1β response to infection." (PMID 27559003, 2017). "IL-1β and KC secretion was markedly increased in och1Δ/Δ-challenged newborn mice at day 7 post-infection compared to the WT CLIB, and the och1Δ/Δ+OCH1-challenged mouse groups." (PMID 28713338, 2017). "After 6 h of infection, we found significantly decreased levels of pro-inflammatory cytokines, including IL-1β, IL-6, IL-12, IFN-β, and TNF-α induced by MAP 0908 in BMDM at both translational and transcriptional levels." (PMID 29375563, 2017). "After three and 6 h of infection IL-1β concentration increased in supernatants reflecting caspase-1 activation." (PMID 28874114, 2017). "flexneri, we observed il-1b:GFP-F expression in neutrophils, macrophages, and epithelial cells surrounding the infection site, indicating that leukocytes and other cell types can be a source of il-1b during S. flexneri infection." (PMID 28650995, 2017). "Some Leishmania molecules, such as lipophosphoglycan (LPG), seem to repress IL1-α, IL-1-β and IL-12 production during infection via TLR2." (PMID 29379478, 2017). "The induction was much higher in CD103+ DC than in CD11b+ DCs and neutrophils, showing that CD103+ DCs are more active in producing IL-1β than other two cell types in response to infection." (PMID 28671985, 2017). "In infected mice, TFF1 is initially upregulated in gastric antrum in the acute phase of infection, along with IL-1β and IL-6." (PMID 29085807, 2017). "Caspase-4 pro-enzyme and pro-IL-18 protein expression was found to be constitutive, whereas pro-IL-1β was induced by P. aeruginosa wild-type infection, reduced by infection with the ΔpopB mutant and very weakly induced by infection with the PA14 ΔflgK mutant." (PMID 28469996, 2017). "In this context, it is conceivable that the enhanced release of IL-12, TNF-α, IL-1β, and IL-6 by ΔesxB infection likely promotes a robust Th1 and Th17 response, whose crucial role in the immunity against S. aureus has been demonstrated by several studies." (PMID 28785545, 2017). "The levels of IL-1α, IL-1β, IL-6, and IL-18 were unchanged or increased in Ccr2-/- mice during infection, likely reflecting increased cytokine production by other immune cell types in response to the substantial increase in bacterial load." (PMID 28384349, 2017). "In our study, expression of TLR4, TLR5, NLRC4, caspase-4, and matured IL-18 and IL-1β cytokines was induced in hCFs after infection with P. aeruginosa wild-type strains." (PMID 28469996, 2017). "Infection of hCFs with P. aeruginosa PAO1 induces significant extracellular release of the cytokine IL-1β." (PMID 28878761, 2017). "In conclusion, BTV-8 infection induces an inflammatory response in the host characterized by increased IL-6, IL-12 and CXCL10 levels, but IL-1β levels only increased after the third infection." (PMID 28662714, 2017). "Pretreatment of neutrophils with the NOX2 inhibitor diphenyleneiodonium (DPI) led to a substantial increase in IL-1β protein release upon infection with YL yeast to concentrations that were comparable to induction by WT hyphae." (PMID 28314592, 2017). "We demonstrate that knockout of caspase b, which enhances processing and secretion of il1β, increases bacterial burden and prevents macrophage migration to sites of infection in a process that results in extracellular growth of the mycobacteria." (PMID 28747644, 2017). "Caspase-1 activation enables the processing and secretion of the proinflammatory cytokine interleukin 1β (IL-1β) to control infection." (PMID 28650995, 2017). "All of the antibiotics reduced significantly (P < 0.05) IL-1β secretion by hCF infected with a Multiplicity Of Infection (MOI) = 1 of PAO1." (PMID 28878761, 2017). "IL-1β, one of the most important pro-inflammatory cytokine, contributes to host defense against infection by augmenting antimicrobial properties of phagocytes." (PMID 28491061, 2017).
infection (continued). "It has been demonstrated that IL-1β is a key regulator of T-cell cytokine production, can restrict bacterial replication in macrophages, and recruits neutrophils to the site of infection." (PMID 29209310, 2017). "We found LPS priming can recover the expression of the repressed the cytokines (TNF-α, IL-6 and IL-1β) after Ms_PE_PGRS41 infection." (PMID 28440335, 2017). "Here, we used a set of isogenic GAS mutants and a macrophage infection model and report that streptococcal NADase inhibits the innate immune response by decreasing inflammasome-dependent interleukin 1β (IL-1β) release from infected macrophages." (PMID 28720729, 2017). "As we have previously reported, infection of Normal Human Bronchial Epithelial (NHBE) cells with human rhinovirus resulted in the release of significant levels of IL-1β and IL-18." (PMID 28830544, 2017). "Collectively, our observations of heightened ASC speck formation, IL-1β secretion and cell death highlights the importance of WASp-mediated actin assembly in regulating inflammasome function during infection and inflammation." (PMID 29146903, 2017). "Lack of HDAC6 also decreased the relative mRNA levels of the pro-inflammatory cytokines TNFα, IL-1β and IL12p40, indicating impaired cytokine activation after infection." (PMID 29281743, 2017). "At 3 h, the levels of il-18 and il-1β cytokine genes induced by PA14 wild-type infection of hCF were ~3-fold higher than the levels induced by PAO1 wild-type (P < 0.05)." (PMID 28469996, 2017). "The cytokine cascade events following B. pseudomallei infection has been studied in several animal models and show an up regulated mRNA expression of inflammatory cytokines such as IL6, IL12, IL10, IFNγ, TNFα and IL1β within 72 hours of infection." (PMID 28628607, 2017). "Markers of inflammation including neutrophil infiltration and proinflammatory cytokine production in the BALF, such as TNF-α, IL-1β and IL-6, were determined 8 and 24 hours post-infection." (PMID 28638106, 2017). "Interleukin (IL)-1β and IL-6 are both pro-inflammatory cytokines whose levels have been shown to increase within hours of infection in crticially ill patients and are inversely related to serum Ca concentrations." (PMID 28993435, 2017). "We have found that P. brasiliensis promoted a NLRP3 inflammasome-dependent caspase-1 activation to release the bioactive IL-1β, and IL-1R1−/− mice displayed a slightly increased survival rate to infection compared with the C57BL/6 mice." (PMID 28871251, 2017). "We found that the levels of IL-1α, INF-γ, TNF-α, MCP-1, IL-1β, IL-10, IL-6, IL-27, and IL-17α in the lungs post infection were significantly different between alcohol- and pair-fed mice." (PMID 28604843, 2017). "En outre, l'infection amibienne a augmenté pNF-κB et interleukine-1β (IL-1β) et a montré une tendance à diminuer hémoxigénase-1 (HO-1), mais pas Nrf2." (PMID 29185982, 2017). "This type I IFN has been shown to directly inhibit IL-1β transcription and IL-1β processing through the inflammasome in response to multiple infections, decreasing host defense in certain infections, but diminishing systemic inflammation in response to others." (PMID 28704551, 2017). "Infection of Mf4/4 macrophages with both strains led to caspase-1 activation and IL-1β and IL-18 production, as well as activation of caspases-3, -7, -8, and -9." (PMID 28280602, 2017). "TNF-α stimulates the production of interleukins that participate in the response to infection or injury, and IL-1β acts on macrophages to release IL-6 and IL-8 related to the pathogenesis of various inflammatory diseases." (PMID 28086859, 2017). "After intratracheal infection with C. neoformans 52D, the level of IL-1β expression was 11-fold higher in the lungs of resistant SJL/J inbred mice compared to the susceptible C57BL/6 inbred strain." (PMID 29403476, 2017).
infection (continued). "Differently from BMDM infection, conidia alone induced IL-1β secretion in BMDCs, suggesting that it acts as both the first and the second signal for inflammasome activation in this cell type." (PMID 29209318, 2017). "Our results demonstrate that TFF1 is up-regulated in the acute phase of infection together with IL-1β and IL-6, while is down-regulated in the chronic phase of infection (after 42 days) when IFN-γ, CXCL5, and CXCL15 increase." (PMID 29085807, 2017). "CLEC9A-mediated SYK activation specifically promotes the production of CXCL8 and IL-1β, which are central to neutrophil recruitment and activation during the early stage of infection." (PMID 29065139, 2017). "Astrocytes are important to brain cells that regulate immunocyte recruitment through the release of cytokines or chemokines, such as IL-1β and IL-6, in response to injuries or pathogen infections." (PMID 28950910, 2017). "We found that depletion of IL-1β ameliorated the tissue inflammation in both M. marinum-infected Ncf1-/- and WT mice on day5 after infection." (PMID 29228045, 2017). "The NLRP3 inflammasome is generally triggered by infection or tissue damage and participates in the processing of mature and bioactive IL-1β from its precursor and inactive form (pro-IL-1β)." (PMID 29170665, 2017). "Inflammasome activation-mediated caspase-1 processing and IL-1β cleavage in response to N. caninum infection were observed and were correlated with the time of infection and number of infecting parasites." (PMID 28558839, 2017). "The post-infection modulation of IL-1β level showed a different profile, with higher production induced in BALF than in serum compared with pre-infection levels." (PMID 28241868, 2017). "TNFα and IL-1β levels were highest 24 h after infection and subsequently declined in the further course of culture." (PMID 26739172, 2016). "After infection with the clinical isolate, IL-1β and CXCL2, potent chemoattractants for neutrophils were both significantly reduced by GLY treatment." (PMID 27792814, 2016). "In a similar murine infection trial, some mice displayed a disproportionate reaction to S. chromogenes TA as well, resulting in a high IL-1β response and an intense clinical reaction." (PMID 27176792, 2016). "At 24 h, tonB K. pneumoniae infection also caused levels of induction of IL-6, CXCL1, CXCL2, IL-1β, and MIP-3α secretion that were comparable to those seen after 48 h of infection with WT K. pneumoniae." (PMID 27624128, 2016). "Together, our previous studies and the present one document the existence of a positive feedback loop whereby neutrophils recruited to infection sites promote further neutrophil influx by producing IL-1β." (PMID 27509078, 2016). "When H. pylori invades stomach, IL‐1β production is up‐regulated to favour the initiation and amplification of the inflammatory response to the infection." (PMID 26805397, 2016). "Infection leads to the upregulation of inflammatory cytokines, such as interleukin-1β (IL-1β), interleukin-10 (IL-10), and tumor necrosis factor-α (TNF-α)." (PMID 28105799, 2016). "As expected, compared to uninfected controls, SA infection resulted in the increased expression of IL-1β, IL-6, and CXCL2 and their levels were significantly lower in Pam3 pretreated retinal tissue." (PMID 26865111, 2016). "Molecular platforms called inflammasomes are activated upon cellular infection or stress, triggering the maturation of proinflammatory cytokines such as pro-IL-1β to engage innate immune defenses." (PMID 26818951, 2016). "For the positive control group, the highest expression levels of LITAF, IL-1β and IL-12 were observed at 1 day post-infection and gradually decreased afterwards." (PMID 26799658, 2016). "Upon infection, proinflammatory cytokines that serve as alarm signals (e.g., IL-1β) are secreted from resident macrophages, and recruit phagocytes to infected tissues for clearance of pathogens." (PMID 27796369, 2016).
infection (continued). "Against this background, tumour necrosis factor alpha (TNF-α), which is a first cytokine released during infection activates the downstream expression of other cytokines such as IL-1β and chemokines." (PMID 27529219, 2016). "The mRNAs for MMP3 and IL1B were also upregulated in young hGFs at 6 h post-infection, compared to 0 h, but these inductions were smaller and delayed compared to those observed in old hGFs." (PMID 27391467, 2016). "IL-1β, a prototypical inflammatory cytokine, is induced and activated following infection and tissue damage." (PMID 27609180, 2016). "But the concentration of IL-1β reached the peak (about 2.6-fold, P > 0.05) in CK/SD/w4 infections, and the IL-6 in CK/SD/w3 infections (about 2.8-fold, P < 0.05)." (PMID 27446066, 2016). "Seven days after infection, the expression of IL-1β, IL-6, IL-17, IL-18, and TNF-α mRNA was significantly lower in the jejunum of COS-fed mice compared to those of controls." (PMID 28100936, 2016). "The interleukin (IL)-1β, processed by the NLR family pyrin domain containing 3 (NLRP3) inflammasome, has been identified as a target for pathogenic infection of the inflammatory response." (PMID 28083517, 2016). "The obligate intracellular bacterium O. tsutsugamushi targets and infects macrophages: IL-1β elevation by 2-APB provides an efficient strategy to mitigate this infection." (PMID 27472555, 2016). "Activated caspase-1 controls the maturation and secretion of proinflammatory cytokines such as IL-1β and IL-18, which direct host responses to infection and injury." (PMID 27321752, 2016). "Analysis of infection-induced cytokines, including IL-8, IL-1β, IL-6 and TNF-α in vitro and in vivo revealed that cytokine and chemokine responses were dependent on expression of β-H/C that also elicited severe bladder neutrophilia." (PMID 27383371, 2016). "There was a significant increase at day 7 relative to day 5 post-infection in abundance of interleukins (IL) including IL1B, IL2, IL4, IL5, IL6, IL10 and IL13." (PMID 27311020, 2016). "During late infection stages, the secretion levels of IL-6, IL-1β, and IFN-β in the three clinical samples with neoplasms had significantly increased." (PMID 27252695, 2016). "The IL-1β mRNA expression in normal or HG-culture HGFs was also significantly increased when infected with HGPg, whereas NGPg infection only had a marginal effect on IL-1β mRNA expression in HG-cultured HGFs." (PMID 28083517, 2016). "Blockade of type I IFN receptor or administration of IL-1β to Axl-/- mice restored the antiviral adaptive response and control of infection." (PMID 27350258, 2016). "Infection of eWT or eK201R triggered macrophages to secrete cytokines including IL-18, IL-1β and TNF-α." (PMID 26943369, 2016). "In that regard, as a member of the IL-1 family, IL-1β supports the host’s defense against infection." (PMID 27187378, 2016). "Expression of the IL-1β gene is induced by NF-κB and leads to recruitment of macrophages and neutrophils to the site of infection with consequential increases in local inflammatory responses, commonly associated with clinical paratuberculosis." (PMID 27093613, 2016). "Comprehensive cytokine/chemokine analysis reveals a host response to Ft largely similar between LVS and SchuS4 with significant levels of many factors (e.g., TNFα, IL-1β and IL-6) appearing at 3 dpi onwards during infection." (PMID 27015566, 2016). "Largemouth bass, challenged with Nocardia seriolae (1.0 × 106 cfu/mL), showed a significant increase in IL-1β at 3 and 5 days post infection (dpi) in the spleen, while in the head kidney significant expression was found at 2 and 3 dpi, peaking at 3 dpi." (PMID 27706080, 2016). "Critically, on day 4 post-infection, IL-1β, TNFα, IL-6, CCL2 and CCL5 concentrations were significantly reduced in BAL fluid while IL-6 and IL-18 were reduced in the sera." (PMID 27283237, 2016).
infection (continued). "BCG infection at MOI 0.1 was more efficient to induce the early production of IL-1β, while infection at MOI 1 induced a delay but high level of IL-1β." (PMID 27833923, 2016). "BMDM infection with Escherichia coli also showed increased IL-1β production in Card9−/− in comparison with WT macrophages without affecting pyroptosis, intracellular bacteria counts and TNF-α production." (PMID 27670879, 2016). "Type I IFNs (IFN-α and IFN-β) are potent antiviral signal molecules, although they inhibit antibacterial signaling pathways by suppressing inflammatory components of Th1-type immunity, such as IL-1α, IL-1β and type II interferon, and promote infection by Mtb." (PMID 27409673, 2016). "At 2 h post infection Card9−/− BMDMs produced detectable IL-1β after infection with both bacterial strains although the level was much reduced in cells infected with the ΔfliCΔfljBΔprgJ mutant." (PMID 27670879, 2016). "In response to R. australis, mouse macrophages secrete IL-1β and IL-18 as late as at 8 h p.i. after a high dose of infection and at 12 h after a low dose of infection." (PMID 27362650, 2016). "Previous results showed a significant increase of tnfa, il1b, and il10 over time in zebrafish larvae infected by E. ictaluri up to 3 days post-infection." (PMID 27790411, 2016). "R. australis induced significant secretion of IL-1β at 8 h p.i. upon infection at a high dose (MOI of 6) and at 12 h p.i. at a low dose (MOI of 2)." (PMID 27362650, 2016). "IL-1β peaked 24 h post-infection, which was 17-fold higher than in 5b ΔAdh-infected PAMs and PBS controls (P < 0.05)." (PMID 27046446, 2016). "The increased susceptibility of Casp1/11-/-, Asc-/-, and IL-1r1-/- mice to Ft LVS infection in this study and IL-1β-/- mice in a previous study clearly underscore the critical requirement of IL-1β/IL-18 for protective immunity." (PMID 27926940, 2016). "The cytokines TNF-α and IL-1β in teleosts are powerful proinflammatory cytokines released by several immune cells during infection or tissue damage and are involved in a diverse range of inflammatory and infectious conditions." (PMID 28105799, 2016). "IL-1β secretion was elevated in BMDMs infected with WT S. Typhimurium, but markedly reduced, as expected, in BMDMs after infection with the ΔfliCΔfljBΔprgJ mutant." (PMID 27670879, 2016). "Many different cell types, including resident and inflammatory cells, can produce IL-1β during infection." (PMID 27509078, 2016). "This study proposes a new, genetic basis of susceptibility, exemplified by the disease phenotype in Asc-/- or Nlrp3-/- mice or resistance in Il1b-/- mice that were protected from infection." (PMID 27732661, 2016). "In a previous study we showed that MAP induced peak phagosome acidification concomitant with calcium-dependent IL-1β secretion within 30 min p.i. to recruit macrophage recruitment to the site of infection." (PMID 27597934, 2016). "Curiously, macrophages from Aim2-/- mice produced more IL-1β than wildtype cells in response to LVS infection but IL-1β production following SchuS4 infection was limited." (PMID 27926940, 2016). "In all cases the distribution of the IL-1β expression after infection was highly representative because 80% of the larvae injected in the same site presented similar GFP distribution." (PMID 27540375, 2016). "IL1β, which is produced as an inactive precursor (pro-IL1b), is cleaved by the interleukin-converting enzyme and secreted in its mature form following tissue damage, infection and inflammation." (PMID 27072893, 2016). "NQO1 expression was increased after mycobacterial infection, and NQO1 knockdown increased macrophage differentiation, NF-κB activation, and the secretion of pro-inflammatory cytokines TNF-α and IL-1β in response to infection." (PMID 27297123, 2016). "Expression levels of IFN-β and IL-1β were highest in secondary infection with serotype 3, followed by secondary serotype 4 infection." (PMID 27034012, 2016).